CD27 (CD27 molecule)
Diseases named in the same sentence as CD27 in open-access papers (continued):
Sharing a sentence is not in itself a finding about the gene and the disease.
tumor (continued). "Additionally, higher levels of Treg cells were found in the primary tumor tissue, expressing elevated levels of costimulatory genes associated with immune checkpoints (CD27, ICOS, TNFRSF4, and TNFRSF18) and exhaustion markers (CTLA4 and TIGIT)." (PMID 40303346, 2025). "Notably, CD70 expression did not correlate with immune cell densities within either the stroma or tumor nests, whereas high CD27 expression was associated with reduced CD45 + and CD8 + cell densities in the stroma." (PMID 40205178, 2025). "Whereas naïve lung and blood mostly contained differentiated NK cells, metastatic lungs harbored a large cluster of tumor-associated NK cells (Tumor NK) expressing markers of less differentiated NK cells (Emb, Cd27, Ccr2, Cd28, Thy1 or Sell), confirming our flow cytometric data." (PMID 41145419, 2025). "Our analysis may imply that loss of tumor cell surveillance at the stage of asymptomatic BR is associated with an increase in the percentage of lymphoid subpopulations including CD27+ T cells, memory B cells, and NK/NKT cells." (PMID 35807007, 2022). "Also in HCC, CD27+ Bregs present in the tumor microenvironment cause the decrease and dysfunction of CD8+ T cells through IL-10 production, and their level is correlated with the disease stage and early recurrence." (PMID 36618354, 2022). "However, in the later stage Teff, persistent recurrent exposure of the immunogenic tumor antigens leads to a gradual loss of the expression of CD27 and CD28, converting DP cells to DN cells." (PMID 34593620, 2021). "As we demonstrate high expression levels of CD70/CD27 in other tumour types using our uniform IHC method, these results underline the potential of anti-CD70 immunotherapy not only in AML, but also in other haematological malignancies and solid tumour types where CD70 is overexpressed." (PMID 31652572, 2019). "Specifically, we showed that tumor cell lines derived from various tissues directly induce phenotypic and functional changes associated with T cell dysfunction characterized by the loss of CD27 and CD28 expression and telomere shortening." (PMID 28806909, 2017). "In addition, CD27 signaling in Treg (discussed further below) has been implicated as a means of tumor escape, further emphasizing the need to fully characterize the functional activity of CD27 agonist mAbs." (PMID 26500773, 2015). "CD27 signaling has also been implicated in Treg expansion in mice] where increased numbers of Tregs in tumor infiltrating lymphocytes, spleens and nodes were reported in CD27(+/+) wild type mice relative to CD27(−/−) mice suggesting that CD27-CD70 signaling increases the number of Tregs." (PMID 26500773, 2015). "Additionally, NK cell CD27 was downregulated upon increased tumour burden which corresponded with impaired cytotoxic capacity in vitro, suggesting CD27 expression may associate with prognosis." (PMID 38440738, 2024). "Altogether, these data strongly suggest that murine CD27− γδ17 T and human Vδ1+ T cells are particularly susceptible to ROS-mediated suppression because of their low basal glutathione levels, thus providing novel cues on how to limit their cancer-promoting functions in the tumor microenvironment." (PMID 29750788, 2018). "CD27 expression marks superior suppressive naturally occurring Tregs (nTregs) while in cancer, this showed to be a prognostic marker for tumor progression." (PMID 41878425, 2026). "This humanized construct effectively induced antigen-specific cellular immune responses and suppressed tumor growth in CD28/4-1BB/CD27 triple-humanized mice." (PMID 42079630, 2026). "Especially, a positive correlation between ACAA1 expression in tumor cells and six immune checkpoint-related genes, namely CD27, PDCD1, CD86, BTLA, TIGIT, and CD28, on immune cells within the tumor microenvironment." (PMID 41277949, 2025).
tumor (continued). "In contrast, cytotoxic NK cells, which exhibit a CD56dim phenotype with CD11b+ and CD27− markers, are highly cytotoxic and primarily involved in the direct killing of infected or tumor cells." (PMID 39941044, 2025). "Our findings demonstrated that CD70 and CD27 are expressed in tumor cells and within the TME of SCLC, with distinct expression patterns." (PMID 40205178, 2025). "CD70-CD27: We observed that tumor B-cells expressed high levels of CD70, which interact with CD27 to provide coinhibitory signals to CD8+ Teff cells." (PMID 40078987, 2025). "Of importance, whereas frequencies of terminal mature CD27-CD11b+KLRG1+ NK cells in the spleen were still reduced in Nr2f6-deficient mice, they were rescued to wild-type controls in the blood and the tumor." (PMID 39920136, 2025). "CD70 expression was predominantly found within tumor nests and to a lesser extent in the stroma, while CD27 was primarily located in the stromal compartment." (PMID 40205178, 2025). "In this context, tumour infiltrating senescent T lymphocytes can affect B-cell (CD19+/CD20+) activation and their subsequent differentiation into CD27+/CD38+ cells, ultimately leading to a deficiency in antibody production and inefficient adaptive responses." (PMID 41372921, 2025). "NKG2D CAR-T cells with the addition of CD27 as a co-stimulatory domain have anti-tumor activity against triple negative breast cancer in vitro and in vivo MDA-MB-231 fLuc xenograft NOD-SCIDIL2γc-/- (NSG) mouse model." (PMID 40612946, 2025). "Further, CD27+ CD4+ T cells and LAG-3+ CD8+ T cells displayed significant positive correlations between PB and tumor tissues, whereas a positive association of 4-1BB+ CD4+ or OX40+ CD4+ T cells derived from ascites and tumor samples was detected." (PMID 41221283, 2025). "CD27 expression—a costimulatory molecule vital for T cell memory, was reduced in all tumor-bearing groups, including treated ones." (PMID 40733014, 2025). "We have previously shown that the biomarker CD27 can be measured in plasma and reflects the state of the immune system in the tumor." (PMID 40148586, 2025). "Further GEPIA analysis revealed Decreasing naïve B cells but increasing memory/plasma cells from normal, adjacent normal and tumor tissue, and increasing CD27/IREB2 in memory/plasma cells across these tissues." (PMID 41377765, 2025). "As for activation markers, the expression of CD38 was increased in all T cell subtypes in the tumour sample, while HLA‐DR and CD27 were also up‐regulated in numerous T cell subsets." (PMID 39934971, 2025). "CD70, signaling through its T-cell costimulatory receptor CD27, engages diverse functions in T-cell immunoregulation, while CD70–CD27 dysregulation has been associated with tumor progression." (PMID 40519930, 2025). "A correlation was found between plasma sCD27 levels and CD27-CD70 interaction or combined CD70-CD27 expression intratumorally in renal and nasopharyngeal carcinoma, respectively, suggesting a tumor origin of plasma-soluble CD27." (PMID 40148586, 2025). "This pattern is associated with increased lung tumor metastasis rates in the global CD27 KO mice, suggesting that increased tumor burden induced higher levels of cytokines in these mice." (PMID 39105866, 2024). "We observed distinct disparities in tumor burden and treatment outcomes between the CD27- and CD27 + cohorts." (PMID 38504180, 2024). "CD27 wields influence on MM tumor cells directly and has a pronounced effect on the MM microenvironment." (PMID 38504180, 2024). "Agonistic targeting of CD27 to stimulate anti-tumour T cell reactivity has been studied on a smaller scale when compared to other ICS-mediated T cell engagement." (PMID 38440738, 2024). "AHNAK2 and SLC2A1 were primarily expressed in epithelial cells, while CD27 and LTB were predominantly associated with T cells, potentially influencing tumor immunity." (PMID 39593730, 2024).
tumor (continued). "Further studies with diverse tumor models are required to determine what cell types contribute to CD27-dependent tumor immunity." (PMID 39105866, 2024). "We observed significantly accelerated tumor growth in the CD27 KO group compared to WT controls or the CD8Cre-CD27fl group." (PMID 39105866, 2024). "B10 cells have been shown to promote tumour growth, as tumour infiltrating CD27+ CD10- Bregs inhibited inflammatory cytokine production by effector T cells in GC." (PMID 39346706, 2024). "Western blot and immunofluorescence assays showed that the hub gene CD27 was upregulated in these tumor-specific T cells." (PMID 39033098, 2024). "This in combination with the superior anti-tumor function of CD27+Ly6C+ γδ T cells provides a rationale to use mice for the study of anti-tumorigenic human γδ T cells." (PMID 38816652, 2024). "Given the recent successes of immunotherapy in MM treatment, combining CD27 targeting with immunotherapy to modulate T and NK cell activity in the tumor microenvironment appears to be a promising approach." (PMID 38504180, 2024). "We have found that global CD27 KO mice succumbed to significantly accelerated tumor growth compared to WT controls." (PMID 39105866, 2024). "In HCC tumours CD27 was found expressed on tumour-infiltrating B and T cell but the majority of CD27+ TILs were CD3+ T cells." (PMID 38440738, 2024). "By contrast, tumor size increased to 75% from baseline in only ~33% of CD27+Ly6C+ γδ T-cell-treated mice." (PMID 38816652, 2024). "The frequencies of aMBCs (CD19+CD27‒IgM‒) were higher in patients with tumor size ≤2cm (T1) and tumor size >2cm (T2) in comparison to the control group." (PMID 38702630, 2024). "Another study also showed that Treg-derived CD27 limited antitumor immunity, and ablation of Treg-expressed CD27 synergized with PD-1 blockade to improve cytotoxic T lymphocyte-mediated tumor control." (PMID 39105866, 2024). "The ability of CD27+Ly6C− and CD27+Ly6C+ γδ T cells to control tumor growth in vivo was tested with the E0771 model." (PMID 38816652, 2024). "CD27+ IFNγ-producing γδ T cells utilize glycolytic metabolism for energy, and glucose enhances their anti-tumor activity via mTOR regulation of T-bet, EOMES, and NKG2D expression." (PMID 38816652, 2024). "Many are designed to bring immune cells in proximity with tumor cells by targeting both immune markers (CD137/4-1BB, CD27, PD-1, OX-40) and tumor markers (B7-H3, CD47, PD-L1, 5T4, ROR1, claudin, GPC3, HLA-G, PSCA)." (PMID 38254823, 2024). "On the other hand, it is also possible that reduced levels of Treg cells in the tumor microenvironment alleviated immune suppression of other lymphocytes, which produced higher levels of effector molecules via CD27-independent mechanisms." (PMID 39105866, 2024). "In this context, we aimed to further delineate the role of CD27 signaling in CD8 + T cells in tumor immunity." (PMID 39105866, 2024). "We observed a significant increase in metastatic tumor nests in the lungs of CD27 KO mice compared to WT controls or CD8cre-CD27fl mice." (PMID 39105866, 2024). "Conversely, CD27+Ly6C+ γδ T cells were able to slow tumor growth and extend the survival of tumor-bearing mice when compared to control." (PMID 38816652, 2024). "CD27, a prominent protein in the tumor microenvironment, modulates cellular activity by engaging with CD70." (PMID 38504180, 2024). "Research has shown that tumour-derived γδ Tregs can induce phenotypic changes in T cells, such as the downregulation of CD27 and CD28, leading to the senescence of responsive T cells." (PMID 39678507, 2024). "CD27 has been demonstrated to be co-expressed with CD38 in HCC tumours, potentially delineating NK cells." (PMID 38440738, 2024). "Our results demonstrate that endogenous CD27 signaling inhibits tumor growth and metastasis via CD8 + T cell-independent mechanisms, presumably through stimulating antitumor activities of other types of immune cells." (PMID 39105866, 2024).
tumor (continued). "Specifically, advanced-stage patients in the CD27 + group manifested increased tumor burdens and diminished therapeutic efficacy." (PMID 38504180, 2024). "The current study aims to investigate the role of endogenous CD27 signaling in tumor growth and metastasis." (PMID 39105866, 2024). "CD27 expression was upregulated in tumor samples, and a high expression level was determined to be an independent protective factor for survival." (PMID 38909269, 2024). "Together, these results indicate that endogenous CD27 signaling in the host also suppresses tumor metastasis via CD8 + T cell-independent mechanisms." (PMID 39105866, 2024). "To further validate these findings, we performed repeated injections of CD27+Ly6C− or CD27+Ly6C+ γδ T cells into E0771 tumor-bearing Tcrd−/− mice, then analyzed these cells from tumors." (PMID 38816652, 2024). "Meanwhile, studies have found that CD27+γδT cells secrete IFN‐γ to inhibit tumor cell growth, while CD27−γδT cells produce IL‐17." (PMID 38604998, 2024). "Nevertheless, CD27 agonistic antibodies exhibit anti-tumour functionality in both pre-clinical in vitro and in vivo models by enhancing CD27-mediated ICS and depletion of Tregs via ADCC." (PMID 38440738, 2024). "In tumor-bearing mice, this CD70 interacts constitutively with CD27+ Tregs during tumor development, thereby promoting Treg expansion and preventing cytotoxic T cell responses." (PMID 37545491, 2023). "This antibody was shown to exert antitumor immunity as well as direct killing of CD27+ tumor cells in animal models and it is currently evaluated in patients with hematologic malignancies." (PMID 37575254, 2023). "In this study, we identified that cytotoxic and exhausted CD8+ TILs with a tumor-reactive phenotype express the co-stimulatory receptor CD27 across various EGFR+ cancer subtypes." (PMID 37545491, 2023). "In the list of downregulated DEGs, low CD27 expression in malignant plasma cells has been reported to be correlated with poor prognosis while the tumour suppressor gene WWOX has been found downregulated due to translocations or deletions." (PMID 37006302, 2023). "The potent anti-tumor activity of this antibody was shown in preclinical and clinical studies, where targeting CD27 in hematologic and solid tumors led to increased survival and stable disease." (PMID 37575254, 2023). "In line with the CD27 crosslinking requirements, previous studies with syngeneic mouse tumor models have shown that Varlilumab induces FcR-engagement-dependent tumor regression and facilitates long-term anti-tumor immunity." (PMID 37545491, 2023). "Expression of co-stimulatory CD27 decreased with proximity to the tumour but was significantly expressed in stromal regions, and a CD27 agonist such as varlilumab was suggested by the authors as a potential means to exploit this." (PMID 37835491, 2023). "All ATC samples expressed CD27 in the surrounding lymphocyte subsets and were infiltrated by the tumor." (PMID 37007127, 2023). "FOXP3 was found to co-localize with tumor-infiltrating CD20+CD27+ B cells to promote effector and memory T cell differentiation and enhance B cell and NK cell activation and function." (PMID 38067301, 2023). "ACM derived from OGJ patients with early-stage tumours significantly increased the expression of CD27 on the surface of CD4+ T cells compared with untreated cells (untrx: 41.00 ± 3.5 vs. early-stage: 57.55 ± 5.0%, p = 0.01)." (PMID 36790524, 2023). "OAC patient-derived PBMCs co-cultured with OE33 OAC cells upregulated LAG-3 and downregulated the co-stimulatory marker CD27 on T cells, highlighting the direct immunosuppressive effects of tumour cells on T cells." (PMID 36445478, 2023). "In theory, targeting CD27 can induce anti-tumor responses by either agonizing the effector cells or depleting the Tregs dependent on the level of expression on individual cell populations similar to targeting other members of the TNFRSF." (PMID 37180119, 2023).
tumor (continued). "These cells are unable to respond to stimulation or recognition of tumor antigens because of the downregulation of the co-stimulatory molecules CD27 and CD28 and the upregulation of inhibitory molecules, including LAG-3 and PD-1." (PMID 38136380, 2023). "A significant level of CD70 can be detected in various types of tumor tissues and CD27 is expressed on Treg cells, but CD70 expression is low in normal tissues." (PMID 37849799, 2023). "Emut Vax skewed macrophages towards the anti-tumor M1 macrophage subset and enhanced the proportion of cytotoxic CD27-CD11b+ NK cells while decreasing the immature CD27+CD11b- NK cells." (PMID 36875137, 2023). "CD27 is important for T cell co-stimulation and agonistic targeting, and its expression reduces tumor growth in mice." (PMID 37620318, 2023). "The majority of tumor-infiltrating TEMRA cells were CD27+/CD28+ double-positive, which is a characteristic of poorly differentiated effector cells." (PMID 38136380, 2023). "Second-generation NGK2D-CAR-T cells with a 4-1BB or CD27 co-stimulatory structural domain increased T cell persistence and tumor regression and demonstrated strong antitumor activity in TNBC cell cultures and mouse xenogeneic models." (PMID 37457288, 2023). "In an established single-cell tumor immune atlas from a range of cancer types, CD27 expression was prominent in a subpopulation of regulatory T cells (Tregs), terminally exhausted CD8+ T cells, as well as cytotoxic CD8+ T cells." (PMID 37545491, 2023). "The antigen-dependent and tumor-selective cross-linking with CD27 was previously reported to functionally replace the FcγR dependent agonistic activity reported for several TNFRSF targeting antibodies." (PMID 37545491, 2023). "Tumour-infiltrating and circulating T cells had significantly lower CD27 expression and significantly higher CD69 expression post-FLOT and post-CROSS treatment." (PMID 35986757, 2023). "When comparing tumor-bearing KB1P mice with tumor-free WT mice, the proportion of CD27− γδ T cells and the total number of Vγ4+ and Vγ6+ cells was higher in the lungs of tumor-bearing mice." (PMID 36480166, 2023). "We also unveiled that CD70-targeted cusatuzumab treatment destabilized Tregs in a manner dependent on the CD70 expression level on tumor cells, the CD27 expression level on CD4+ T cells, and the CD4+/CD8+ ratio in the TME." (PMID 37024479, 2023). "On a different note, the tight regulation that governs co-stimulatory CD70/CD27 signaling can be aberrantly altered to have tumor-favoring consequences." (PMID 37345056, 2023). "Once CD27xEGFR binds to EGFR+ cancer cells, the CD27-targeting domain can provide multivalent and tumor-localized crosslinking of CD27, potentially reducing off-tumor side effects." (PMID 37545491, 2023). "This bsAb was designed to be minimally active ‘en route’, while providing multivalent and tumor-localized crosslinking of CD27 when bound to EGFR+ cancer cells." (PMID 37545491, 2023). "This was also observed in the CD4+ T cell compartment, with a decrease in the percentage of tumour-infiltrating CD3+CD4+CD27+ post-FLOT chemotherapy compared with the treatment-naïve tissue (16.22 ± 3.6 vs. 4.64 ± 1.8%, p = 0.03)." (PMID 35986757, 2023). "CD27 agonism or antibody-mediated depletion of granulocytic cells leads to a better tumor control after vaccination with anti-PD-1 therapy, further improving effectivity." (PMID 38001616, 2023). "Tumor-evoked CD19+CD81+CD27+pSTAT3+ regulatory B cells producing IL-10 and TGF-β suppressed T cell responses in the spleen and supported tumor growth in experimental fibrosarcoma." (PMID 38136307, 2023). "In the current study, CD27xEGFR was demonstrated to have high-affinity binding to EGFR on EGFR+ tumor cells and to CD27 on CD27+ T cells." (PMID 37545491, 2023). "Pre-clinical findings showed that IMM40H has a higher binding ability, stronger ability to block the interaction of CD70/CD27, and stronger ability to kill tumor cells than other CD70 competitors." (PMID 37849799, 2023).